IL10 (interleukin 10)
Diseases named in the same sentence as IL10 in open-access papers (continued):
Sharing a sentence is not in itself a finding about the gene and the disease.
Obesity (continued). "Since obesity and metabolic stress increase circulating pro-inflammatory cytokines, we asked if islet T cells and B cells maintained IL-10 expression under the inflammatory conditions in the DIO model." (PMID 35145521, 2022). "Similar to obesity, the IL‐17/IL‐10 ratio is increased in COVID‐19 cases, even in deceased patients, as compared to those who improved." (PMID 35837843, 2022). "In a recent study, it has been showed that ablation of IL‐10 improved insulin sensitivity and inhibited diet‐induced obesity, also in another study, IL‐10 was indicated to be decreased in childhood obesity." (PMID 35266264, 2022). "The aim of the present study was to investigate the relationship between SNPs of the IL10 and IL10RB genes and the risk of obesity in young men." (PMID 35205336, 2022). "IL-10 is a well-defined anti-inflammatory cytokine with protective effects in liver injury, but high levels of circulating IL-10 have sometimes been reported in subjects with obesity." (PMID 35806447, 2022). "When further considering the evidence regarding Bregs as critical for controlling adipose tissue homeostasis in animal models, a decrease in peripheral blood transitional B cells and their IL-10 production has also been documented in human obesity." (PMID 35960996, 2022). "We show that WAT and serum IL-10 levels of healthy men and women are the same, but a gender-specific effect is observed in connection to obesity." (PMID 36313784, 2022). "The cytokine granulocyte-colony stimulating factor (G-CSF) is known for its anti-obesity effects, while IL-10 is anti-inflammatory and is present at lower circulating levels in obese subjects." (PMID 35456006, 2022). "Tissue levels of IL-10 also differed significantly by obesity status (p = 0.004), where obese animals demonstrated significantly lower levels." (PMID 36293536, 2022). "GSEA analysis showed that LINC01615 was associated with most of the immune pathways, such as the IL6 signaling pathway, IL1 and megakaryocytes in obesity, and the biocarta IL10 pathway." (PMID 35794984, 2022). "Serum IL-10 levels are significantly reduced in patients with obesity and metabolic syndromes such as hypertriglycemia." (PMID 35909571, 2022). "The level of IL-10 in the obesity group was much lower than that in the control group, while the levels of TNF-α, IL-6, and LPS showed a significant upward trend." (PMID 35600958, 2022). "A higher level of IL10 expression in obesity and insulin resistance was observed in both human and mouse WAT." (PMID 35205339, 2022). "Logistic analysis revealed that after adjusting for sex, age, hypertension, obesity, as well as IL-10, IL-4, and IL-6, an increased plasma level of TNF-α was significantly associated with sarcopenia (P < 0.001)." (PMID 36160136, 2022). "In contrast, other studies indicated that IL10 correlates positively with obesity in young and adult females." (PMID 35955698, 2022). "Women with obesity and T2D had significantly higher circulating IL-10 compared to men belonging to the same metabolic subgroup." (PMID 36313784, 2022). "IL-10 was found to be lower in individuals with obesity but higher in AN compared to normal weight controls." (PMID 35911732, 2022). "Compared with the control group, the level of anti-inflammatory factor IL-10 in the cord blood was decreased in the obesity group, while the levels of proinflammatory factors TNF-α, IL-6, and LPS were increased." (PMID 35600958, 2022). "In our study, the results of ELISA illustrated the effects of exercise on TNF-α, IL-1β, and IL-10 levels in the serum of mice with HFD-induced obesity." (PMID 36145106, 2022). "Logistic analysis after adjusting for sex, age, hypertension, obesity, and interleukin (IL)-10, IL-4, and IL-6 levels." (PMID 36160136, 2022). "Among them, GSEA analysis showed that LINC01615 is associated with most of the immune pathways, such as the IL6 signaling pathway, IL1 and megakaryocytes in obesity, and the biocarta IL10 pathway." (PMID 35794984, 2022).
Obesity (continued). "IL-10 release was also significantly higher in women with obesity and T2D compared to men from the same metabolic subgroup." (PMID 36313784, 2022). "Further, IL-10 is an anti-inflammatory factor, which induces M2 activation of macrophages and improves obesity-induced insulin resistance." (PMID 36230963, 2022). "While lean adipose tissue is rich in type 2 and anti-inflammatory cytokines such as IL-10, obesity tips the balance in favor of a proinflammatory milieu, leading to the development of insulin resistance and the dysregulation of systemic metabolism." (PMID 34837070, 2022). "Our results suggest that sex-specific IL-10 regulation by obesity/T2D is mediated at the transcriptional level because mRNA expression was found to be increased in parallel to secretion." (PMID 36313784, 2022). "It seems that a compensatory increase in IL-10 in people with sarcopenia obesity is to counteract chronic inflammation." (PMID 35250869, 2022). "While much remains to be addressed about how microbiota impacts B cell function in obesity, we have previously shown that gut microbiota-derived signals expand IL-10-expressing Bregs in mice." (PMID 35960996, 2022). "The circulating concentrations of inflammation related to obesity (leptin and adiponectin) and (IL-6 and IL-10)-related biomarkers were also analyzed in this study." (PMID 35207221, 2022). "IL-10 actions are related to the reduction of inflammatory events, obesity, and oxidative stress in skeletal muscle." (PMID 36362238, 2022). "Myokines affecting sarcopenic obesity include IL-6, IL-10, IL-15, myostatin, insulin-like growth factor (IGF-1), irisin, FGF-21, and leukemia inhibitory factor (LIF)." (PMID 35250869, 2022). "Feeding induced IL-10 from ATMs, whereas obesity markedly decreased IL-10-producing macrophages in epidydimal WAT." (PMID 36091076, 2022). "This was explained by the finding that IL-10 suppresses the differentiation of adipocyte precursors into beige adipocytes, impeding thermogenesis and promoting obesity." (PMID 35936011, 2022). "These events appear to affect myokines that are effective in sarcopenic obesity such as IL-6, IL-10, IL-15, myostatin, insulin-like growth factor (IGF-1), irisin, and fibroblast growth factor-21 (FGF-21)." (PMID 35250869, 2022). "In summary, there is a sex-specific obesity/T2D regulation of the anti-inflammatory cytokine IL-10 in scWAT and in serum." (PMID 36313784, 2022). "IL-10 was the important anti-inflammatory cytokine, the content of IL-10 was 38.962 ± 6.886 in normal samples, while decreased to 18.902 ± 9.942 in obesity samples, had significant difference between normal group." (PMID 34527688, 2021). "In patients with diabetes and obesity, for example, the likelihood of disease progression increased from 0.1% with low IL-10 and IL-12 (p70) levels to >80% with levels of these cytokines exceeding the 90% sensitivity thresholds." (PMID 34386533, 2021). "Circulating plasma levels of several immuno-modulatory peptides, including TNFα, IL-6, IL-8, IL-10, IL-18 and C-reactive protein, were found to be elevated in human obesity." (PMID 34571976, 2021). "Paradoxically, immune cell–derived IL-10 can drive insulin resistance in obesity by suppressing adipocyte energy expenditure and thermogenesis." (PMID 33351782, 2021). "The decrease in the concentration of Th2 cells observed in obesity results in a decrease in the concentration of anti-inflammatory cytokines, such as interleukin 4 (IL-4), interleukin 5 (IL-5), interleukin 10 (IL-10) and interleukin 13 (IL-13)." (PMID 34564433, 2021). "In the context of obesity, the Treg cell population in AT decreases, resulting in decreased secretion of the anti-inflammatory cytokine IL-10 and leading to AT inflammation." (PMID 34515616, 2021). "Bee bread (0.5 g/kg/day for 12 weeks) has been previously reported to suppress TNF-α and NF-κβ, and increase IL-10 levels in obesity-induced aortic vascular damage and HFD-induced renal damage rats." (PMID 34943134, 2021).
Obesity (continued). "Numerous studies have shown that IL-10 can play an anti-inflammatory role to reduce the incidence of obesity, but recent studies have demonstrated the opposite role of IL-10 in AT." (PMID 34515616, 2021). "Circulating IL-10 levels were analyzed in 5 studies in which 77 participants with overweight or obesity were involved in a training program." (PMID 34948868, 2021). "On the other hand, the mRNA levels of CD206, IL-10, Fizz1, Mrc1 and PPARγ were reduced in obesity group, and PDX treatment significantly increased the levels of CD206, Fizz1 and PPARγ in epididymal adipose tissue." (PMID 35185543, 2021). "We propose a logistic regression model that includes clinical variables (diabetes, obesity, and significant lung involvement) and critical biomarkers [IL-10 and IL-12 (p70)]." (PMID 34386533, 2021). "Treg cells in the intestinal mucosa maintain homeostasis and produce large amounts of the anti-inflammatory cytokine IL-10 and protect against obesity, tissue inflammation." (PMID 34950687, 2021). "Fibrinogen and interleukin-1β as a proinflammatory cytokine and interleukin-10 and nesfatin-1 as an anti-inflammatory cytokine have an important role in the development and prevention of systemic inflammation and incidence of obesity-induced diseases." (PMID 33997019, 2021). "Zucker rats with obesity displayed a renal decrease of NO−, gene expression of eNOS, and anti-inflammatory cytokines, such as IL-10 and IL-4." (PMID 34621463, 2021). "The correlations between gut microbiota and obesity-related indices demonstrated that Firmicutes was negatively correlated with adipose IL-10 level and colonic il-10 expression, whereas it had positive association with hepatic tgf-β expression." (PMID 34863163, 2021). "In Italian whites, the IL10 rs1800872 TT genotype separately and within promotor haplotype “rs1800896, rs1800871, and rs1800872 (TAT/TAT genotype)” predisposes to obesity." (PMID 34834553, 2021). "Based on these findings, M-Obese rats can be considered a substantial obesity model for investigating possible vagal–spleen interactions via IL10 actions and their repercussions on WAT histology and function." (PMID 34248663, 2021). "Our previous work has shown that women with obesity had significantly higher baseline IL-6, IL-10, TGF-β, and IL-12 compared with NWW." (PMID 33764994, 2021). "In the case of IBS with prevailing diarrhea, especially its comorbid course with obesity, cytokine imbalance was observed, which was manifested by a decreased amount of IL-10 in the blood serum and increased levels of TNFα and TGFβ1." (PMID 34621378, 2021). "This imbalance production of IL-6 and IL-10 was also confirmed in mitogen-stimulated B cells in individuals with obesity." (PMID 34206312, 2021). "Of 38 plasma proteins analyzed, six (CCL3, IL-1β, IL-1RA, IL-10, IL-17, and TNFα) were upregulated specifically in ccRCC subjects with obesity versus tumor-free controls with obesity." (PMID 32469992, 2020). "We found that most of the analyzed cytokines (IL-1β, IL-8, IL-10, TNF-α, tPAI-1, MCP-1, and adiponectin) were associated with obesity." (PMID 32545403, 2020). "IL-10 seems to attenuate obesity-mediated inflammation and improve insulin sensitivity in skeletal muscle." (PMID 32272872, 2020). "In mice, WAT depots are relatively rich in regulatory B-cells that express IL-10 which play an important role in regulating inflammation in obesity." (PMID 32455939, 2020). "Having already proven that IL10 depletion promotes thermogenesis and confers diet-induced obesity resistance in mice, they sought to further dissect the role that immune cells play in this process." (PMID 32635651, 2020). "According to the effect of decreased weight and WC previously reported in patients with grade I and II obesity treated with dapagliflozin, we expect a decrease in resistin and IL-6 concentrations and an increase in IL-10 and adiponectin concentrations." (PMID 32059692, 2020).
Obesity (continued). "Further, MAIT cells in both the adipose tissue and periphery from obese patients produced higher levels of IL-17 and reduced levels of IL-10, different from the lean state, suggesting a potential role for MAIT cells in obesity-associated inflammation." (PMID 32499756, 2020). "In summary, Fas-mutant mice are resistant to high-fat diet-induced obesity due to increased IL-4 and IL-10 levels and the promotion of thermogenic protein activity and browning in their adipose tissues." (PMID 32686763, 2020). "Lactobacillus sakei OK67 alleviates HFD-induced blood glucose intolerance, obesity, and IL-10 expression in mice." (PMID 31986244, 2020). "In an animal study, high-fat-diet-induced obesity significantly decreased IL-10 blood levels, while IL-10 treatment reduced inflammation induced by high-fat-diet." (PMID 32824387, 2020). "IL-10 also has efficacy in insulin sensitivity and glucose tolerance in type 2 diabetes with obesity." (PMID 31828157, 2019). "Although lower serum levels of IL-10 were described in obesity, elevated levels of IL-10 have been reported in many inflammatory conditions, indicating potential attempts to inhibit inflammation by downregulating pro-inflammatory cytokines." (PMID 31450770, 2019). "In the context of obesity, B-1 cells have been shown to attenuate insulin resistance via IL-10 and polyclonal IgM production." (PMID 30818779, 2019). "Some dysfunctional eating behaviors (frequent among persons with obesity) predicted concentrations of IL-10, EGF, IL-8 and IFN-γ." (PMID 31450770, 2019). "Regulatory T cells (Tregs) and resident anti-inflammatory (M2-like) polarized macrophages that produce factors such as IL-10 help to maintain insulin sensitivity but are reduced within the VAT during obesity." (PMID 30944419, 2019). "Our results showed that obesity induced the expressions of pro-inflammatory cytokines, decreased the anti-inflammatory cytokine (IL-10) expression, elevated intestinal permeability, altered gut microbiota and exacerbated oxidative damages in colon." (PMID 30909396, 2019). "Reduction of IL-10 level is detected in patients with obesity, dyslipidemia, and insulin resistance." (PMID 29408929, 2018). "Macrophage switch to pro-inflammatory phenotype with increasing obesity also entails a decrease in the anti-inflammatory IL-10 expression in obese adipose tissue." (PMID 30254630, 2018). "Regulatory T-cells represent more than half of all CD4+ T-cells in lean murine adipose tissue, and in obesity, regulatory T-cells accumulate around macrophages, produce IL-4 and IL-10, and promote Th-2 T-cell polarisation." (PMID 29479350, 2018). "The positive correlation of IL-10 with leptin has been documented in countering the progression of obesity and metabolic syndrome and in ameliorating inflammation." (PMID 30405010, 2018). "We determined that female mice have higher basal levels of IL-10 in the hypothalamus and that obesity exacerbates sex differences since IL-10 is further decreased in obese males in the hypothalamus as well." (PMID 30254630, 2018). "Thenceforward, the observation of IL-10 as key cytokine in obesity-related metabolic disorders opens perspectives for designing new therapeutic strategies in to treat childhood obesity and its consequences." (PMID 29895283, 2018). "Adipose tissue iNKT-cells have not been investigated with ageing, but considering that IL-4- and IL-10-producing NK1.1+iNKT-cells decline with obesity, it is possible that ageing has similar effects." (PMID 29479350, 2018). "A very recent study demonstrated that glucagon-like peptide-1 (GLP-1), a gut hormone that is used to treat obesity and diabetes, activates adipose iNKT cells and enhances the secretion of anti-inflammatory cytokines including IL-10 in WAT." (PMID 29951059, 2018). "In parallel, reduced level of IL-10 is detected in patients with obesity, dyslipidemia, and insulin resistance." (PMID 29408929, 2018).
Obesity (continued). "The helminth-induced immune responses mainly stem from the Th2 mediated cytokines IL-4, IL-10 and IL-13, the functions of which in nutrient metabolism and obesity are not fully understood and are an area of active research." (PMID 29545532, 2018). "This study evaluated the importance of TNF-α, IL-6, and IL-10 levels and their association with gene polymorphisms in T2DM disease and the obesity." (PMID 28225860, 2017). "The increase of the proinflammatory plasma cytokines TNF-α and IL-1β as well as the decrease of the anti-inflammatory plasma cytokine IL-10 displayed the low-grade inflammation status which is well known in obesity." (PMID 28357137, 2017). "There is evidence suggesting that IL-10 is involved in T2D-related inflammation as mice engineered to ectopically express IL-10 (via gene transfer) are partially protected from HFD-induced obesity and glucose intolerance." (PMID 29387059, 2017). "On the other hand, M2 macrophages overexpress anti-inflammatory factors such as interleukin-10 (IL-10) and arginase-1to ameliorate insulin resistance in obesity." (PMID 29040966, 2017). "Obesity is often described as a low-grade inflammatory state and consistent with this notion plasma IL-6 was increased, and TNFa (P = 0.14) and IL-10 (P = 0.08) tended to increase, in obese vs. lean mice." (PMID 27351281, 2016). "How these cells function in modulating lung injury or its resolution in obesity remain unexplored; however these cells have been shown to produce IL-10 and participate in resolution of lung injury." (PMID 26956558, 2016). "Proximal tubule AT2R activation is also anti-inflammatory by increasing IL-10 production, which offers renoprotection by preventing early inflammation-induced renal injury in obesity." (PMID 26867007, 2016). "In the present study we also report that obesity and CRC conditions are associated with enhanced secretion of the immunosuppressive cytokine IL-10 by adipocytes, and we provide the first evidence that IL-10 content positively correlates with BMI." (PMID 27494857, 2016). "IL-10 has anti-inflammatory properties and enhanced its production by adipose tissue in obesity is a defense mechanism of body to counter-regulate the pro-inflammatory actions of several inflammatory cytokines such as TNF-α, IL-6 and IL-8." (PMID 26909479, 2016). "As a result, after 3 weeks of high fat diet, mice with muscle-specific overexpression of IL-10 develop obesity, but remain insulin sensitive in skeletal muscle." (PMID 27746742, 2016). "The pro-inflammatory cytokines TNFα, IL-1β, and IL-6, considered as highly involved in obesity-related IR and the anti-inflammatory cytokines IL-4 and IL-10 displayed similar levels in CT, OIS, and OIR subjects." (PMID 27111539, 2016). "Based on these results, we conclude that exercise mitigates HFD- induced cardiomyopathy by decreasing obesity, inducing IL-10, and reducing TNF-α in mice." (PMID 25954207, 2015). "Given that obesity is associated with chronic low-grade inflammation, we examined the expression of pro- and anti- inflammatory cytokines TNF-α and IL-10 respectively." (PMID 26588700, 2015). "A follow-up study will also help clarify the interactive effect of serum ferritin and obesity-related inflammation (e.g., IL-10) on testosterone expression in boys." (PMID 26646112, 2015). "In participants with general obesity, levels of IL-4, IL-10 and IL-13 were significantly elevated in participants with low physical activity, even when controlled for BMI which was negatively associated with physical acitivity." (PMID 25781614, 2015). "The aim of this study was to evaluate the association between obesity, measures of body fat content, and serum TNF-α, IL-6, and IL-10 in cSLE." (PMID 24741576, 2014). "Another factor related to obesity is IL10, with a reduction of its concentration being related to the presence of metabolic syndrome." (PMID 24690978, 2014).